CDK6 (cyclin dependent kinase 6)
Diseases named in the same sentence as CDK6 in open-access papers (continued):
Sharing a sentence is not in itself a finding about the gene and the disease.
tumor (603 papers, 1999 to 2026). "L6565 exhibited homozygous CDKN2A loss with retained Rb expression, rendering tumour cells sensitive to CDK4/CDK6 inhibition via palbociclib." (PMID 41924733, 2026). "Its reduced expression is linked to aggressive tumor behavior, as it targets pathways such as Notch1, Notch2, cyclin-dependent protein kinase-6 (CDK6), and proteins involved in Akt/mTOR and Wnt signaling." (PMID 40362297, 2025). "Palbociclib, a selective inhibitor of the cyclin-dependent kinases CDK4 and CDK6, was found to enrich tumor organoids with RB1 mutations." (PMID 40507353, 2025). "CDK4/CDK6 have been implicated in MM cell proliferation, and their inhibition has shown promise in reducing the MM tumor burden." (PMID 39664374, 2024). "First, CDK6 is a cell cycle regulation-related molecule, and its mutations often lead to enhanced cell cycle protein-dependent kinase six activity and tumor growth, consistent with our study’s significant prognostic differences." (PMID 38877400, 2024). "Both gene lists contained genes associated with tumor progression and metastasis, such as CDK6, SNED1, and MTDH." (PMID 37234983, 2023). "Knockout of Sting is sufficient to reverse and partially reverse the anti-tumor effect of Cdk4 and Cdk6 deficiency respectively." (PMID 37833461, 2023). "In some mouse tumor models with specific genetic backgrounds, the loss of CDK4 and CDK6 impedes tumor progression." (PMID 37958642, 2023). "The result showed that tumor growth of both two Cdk6 deficiency cell lines were retarded as compared with those of control MCA205 cells." (PMID 37833461, 2023). "But if the relative expression of TNRC6B is > 5.618 and the relative expression of CDK6 is ≤ 2.841, patients can be classified as high-risk PCa, concretely, 2.4% of subjects can be correctly advanced the presence of an aggressive tumour." (PMID 37978493, 2023). "By doing so, we found a significant decrease in the expression of TNRC6B, AGO1, and CDK6 between the low-risk and high-risk groups, pointing to a decrease in the repressive machinery of microRNAs and proliferation in the aggressive tumours." (PMID 37978493, 2023). "For example, mutations of CDK4 and CDK6, which have been found in melanoma and other tumor types, can disrupt the regular progression of the cell cycle." (PMID 35053461, 2022). "A cationic lipoplex containing miR-29b (LP-miR-29b) has been successfully delivered to A549 cells and xenograft murine model and in both cases, it caused reduced amount of tumor growth as well as clonogenicity by inhibiting the expression of CDK6." (PMID 36303933, 2022). "It is reported that CDK6 protein expression increases several folds than normal cell growth during tumor and tumor-associated diseases like cancer." (PMID 35148332, 2022). "CDKN2B encodes for cyclin-dependent kinase 6 (CDK6), which regulates the cell cycle; its mutation in the cancer setting is associated with uncontrolled tumor growth." (PMID 35159000, 2022). "Meanwhile, cdk6 deficiency can inhibit tumor growth to some extent because this gene is important for cancer cell proliferation." (PMID 35459184, 2022). "At the pan-cancer level, in BRCA, the expression level of CDK6 was positively correlated with tumor neoantigen and negatively correlated with OV, showing that the roles and functions of CDK6 vary in different tumor mutations." (PMID 35480115, 2022). "Ribociclib is a selective strong inhibitor of CDK4 and CDK6, blocks Rb phosphorylation, and causes cell cycle arrest of Rb-positive tumor cells, similarly to palbociclib." (PMID 34445095, 2021).
tumor (continued). "We focused on CDK1/CDK4/CDK6 given that increased expression of CDKs has been associated with many tumor types, and oral, highly selective CDKs inhibitor have already been developed." (PMID 32811807, 2020). "Using a siRNA knockdown approach in combination with metformin treatment, we found that loss of CDK1/CDK4/CDK6 in combination with metformin exhibited enhanced antitumor properties in several tumor cell lines." (PMID 32811807, 2020). "Survival analysis revealed that overexpression of some oncogenes, such as EGFR, CDK6 or CDK4 were associated with poorer prognosis tumours." (PMID 31703248, 2019). "The fact that CDK6 has been implicated in the transcriptional regulation of VEGF-A expression prompted us to analyse tumor angiogenesis." (PMID 30858922, 2019). "CDK6 is a vital factor in mediating G1/S transition in cell cycle, and is linked to the tumor progression as well." (PMID 30829464, 2019). "Another 16% showed significant amplifications or increases in mRNA expression of CDK4, CDK6, and/or Cyclin D1 expression; both these classes of mutations would contribute to an aberrantly overactive cell cycle and, presumably, tumor growth." (PMID 29644000, 2018). "miR-33a is regarded as a tumor suppressor that targets cancer-associated genes involved in cell proliferation and cell cycle progression, such as CDK6, CCND1 and Pim-1." (PMID 27285759, 2016). "Overexpression of cdk6 in tumor cell lines having low cdk6 resulted in decreased levels of mRNAs encoding aldo-keto reductase (AKR)1C1, AKR1C2 and AKR1C3, which are hydroxysteroid dehydrogenases (HSDs) involved in steroid hormone metabolism." (PMID 24848372, 2014). "The inactivation of the CDKN2A gene, which encodes an inhibitor of CDK4 and CDK6, is one of the most common molecular events in human neoplasms." (PMID 22933911, 2010). "They encode inhibitors of the genes CDK4/CDK6 and are believed to play critical roles in cell proliferation and tumor suppression." (PMID 19214202, 2009). "Tumor sequencing performed on a metastatic bone lesion revealed a clonal CDK6 R168C mutation." (PMID 41279360, 2025). "Similarly, miR-3928 inhibits tumor growth and induces apoptosis in OS cells by targeting CDK6, IL-6R and ERBB3 genes, which encode the cyclin-dependent kinase 6, IL-6 receptor and tyrosine protein kinase receptor." (PMID 40868849, 2025). "This might be one underlying mechanism why Cdk6 ΔC shows a tumor-suppressive phenotype compared to Cdk6." (PMID 39898030, 2025). "E7 tumour has the highest expression of CDK6 associated with high levels of CDKN2C." (PMID 36453028, 2024). "Consistent with prior results, Cdk6 deficiency resulted in sharp tumor regression." (PMID 37833461, 2023). "However, the underlying mechanisms of CDK4 and CDK6 in cancer cells involved in regulating anti-tumor responses remain to be elucidated." (PMID 37833461, 2023). "Both p15INK4b and p16INK4a bind to and inhibit CDK4 and CDK6, maintaining the growth-suppressive activity of the Rb tumor suppressor; loss or inactivation of either p15INK4b or p16INK4a contributes to the dysregulation of the CDK4/6-cyclin-Rb pathway and to the loss of cell-cycle control." (PMID 36359251, 2022). "The interaction of CDK4 and CDK6 with D-type cyclins constitutively phosphorylates and inactivates the retinoblastoma protein (Rb), a tumor suppressor, causing the release of its binding partner, E2 transcription factor (E2F), allowing cancer cells to overcome pRb-dependent growth suppression." (PMID 35459184, 2022).
tumor (continued). "To verify the differential expression status between CDK6 and LRP1B in patients with (study group) or without (control group) mutations, we performed IHC staining on tumor tissues from 36 and 34 patients, who were screened and matched using tNGS, from the CDK6 and LRP1B groups, respectively." (PMID 34152098, 2021). "Loss of Cdk6 also affects the migratory capacity of the tumour cell clones." (PMID 30926782, 2019). "In addition, some mutations that were found in other types of tumor like CDK6, PIK3C2B, and ABL2 also occurred in our PDCs." (PMID 28029662, 2017). "Studies have shown that downregulation of p16 gene expression resulted in the loss of its inhibitory effects on CDK4/CDK6, which in turn may lead to malignant, abnormal cell proliferation and accelerated tumor development." (PMID 27199504, 2016). "Similarly, Cdk6 deficiency in TC1 could suppress tumor growth in both immunocompetent mice and immunodeficient mice." (PMID 37833461, 2023). "The CDK6 protein targeted by T. hemsleyanum is also involved in the immune and mutation process of pan-cancer, especially in the regulation of immune cell infiltration, immune checkpoint gene expression, microsatellite instability, tumor mutation burdens, and tumor neoantigens." (PMID 35480115, 2022). "In vivo experiments demonstrated that loss of cdk6 remarkably increased the sensitivity of KB-C2 tumors to doxorubicin by increasing drug accumulation of the tumors, resulting in remarkable inhibition of tumor growth and metastasis, as well as KB-C2 survival in the nude mice." (PMID 35459184, 2022). "Also known as multiple tumor suppressor (MTS1), it can inhibit the activity of cyclin-dependent kinase 4 (CDK4) or CDK6, which thereby inhibit cell cycle and cause G1 retardation of cells, thus inhibiting tumor cell proliferation and facilitating tumor cell apoptosis." (PMID 29299129, 2017). "Concurrently, immunohistochemical (IHC) analysis was conducted to assess the expression profiles of IGF2BP3, CDK6, and Ki67 across different groups of xenograft tumor tissues." (PMID 40083693, 2025). "CDK6 specifically regulates the transcription of tumor-related genes such as vascular endothelial growth factor-A (VEGF-A) and early growth response gene-1 (EGR1), thereby promoting the transcription of genes from G1 to S phase." (PMID 39944826, 2025). "In line, Cdk6 ΔC cells showed similar tumor formation potential as Cdk6 knockout cells when implanted subcutaneously into mice." (PMID 39898030, 2025). "TISIDB analysis revealed strong associations between CDK6 expression and FIGO stage and tumor grade." (PMID 41287970, 2025). "The miR-34a is a key regulator of tumor suppression controlling the expression of several targets involved in the cell cycle (c-MYC, E2F, CDK4 and CDK6), apoptosis (BCL2 and SIRT1) and tumor-associated invasion (c-MET)." (PMID 40755967, 2025). "NUP98-R-positive AML tumor cells also showed sensitivity to CDK6 inhibitors in both in vitro and in vivo models." (PMID 40016600, 2025). "Here we provide a schematic overview on their contribution in tumor progression, since CDK4 and CDK6 have distinct and overlapping functions in tumor development, affecting stemness, angiogenesis, transcription, metabolism, and immune modulation." (PMID 39800748, 2025). "IHC analysis of an EC tissue microarray showed significantly higher CDK6 levels in EC specimens versus normal endometrial tissues, with a positive correlation to tumor grade." (PMID 41287970, 2025). "Their results suggested that in vitro, the CDK4/CDK6 inhibited fibroblasts can induce genotype-dependent tumor cell proliferation and prolonged inhibition of senescent cells in the TME." (PMID 40075679, 2025). "In certain instances, overexpression of CDK6 leads to excessive cell proliferation and tumor formation." (PMID 40083693, 2025). "Preclinical studies showed that CDK6 was highly overexpressed in AML tumor cells and significantly reduced after chemotherapy-induced remission." (PMID 40016600, 2025).
tumor (continued). "The proposed mechanisms include the inhibition of CDK4 and CDK6, blocking Rb phosphorylation, and preventing tumor cells from entering the S phase, thereby inhibiting tumor growth." (PMID 40416598, 2025). "The decrease in C-myc and CDK6 is typically associated with cell cycle arrest and proliferation inhibition highlighting the role of FAM84A in regulating tumor cell proliferation." (PMID 41179292, 2025). "Amplification of or mRNA overexpression of CDK4, CDK6 and/or cyclin D1 was observed in 16% of tumours." (PMID 38612869, 2024). "We demonstrate that STAT1 overexpression induces G1 arrest by downregulating CDK6 expression and suppressing tumor cell proliferation and migration." (PMID 39575303, 2024). "When miR-214-3p levels decreased, high levels of CDK6 promoted tumor initiation and progression, which is essentially a reverse aging process." (PMID 38577599, 2024). "They showed that GPR37 was able to bind to CDK6, which in turn induced cell cycle arrest to promote tumor progression in LUAD58." (PMID 38584220, 2024). "CDK6 amplification is significantly correlated with tumor size and indicates a better prognosis for ESCC." (PMID 38633613, 2024). "Of these, circ_0000984 can up-regulate the expression of CDK6 gene by competitively binding to miR-106b, thereby playing a role in the growth and metastasis of tumor cells." (PMID 39452097, 2024). "CDK6 regulates tumor immune status, metabolism, and cell cycle-related signaling pathways, thereby influencing tumor biological behavior." (PMID 39310261, 2024). "Early studies showed that CCND1 and CDK6 are activated in tumor cells and their expressions are upregulated." (PMID 38711992, 2024). "Consistently, Ki67, MMP2, MMP9, c-Myc, β-catenin, CDK4, CDK6, and Cyclin D1 protein levels in tumor tissues were significantly decreased by SAMD5 overexpression but partially increased by PLK1 overexpression." (PMID 39524172, 2024). "Patient 139 showed a profile with extensive MEI in the tumor and harbored a CDK6 ecDNA and KRAS BFB." (PMID 38744814, 2024). "Targeting CDK6 is a potential pathway for inducing cell cycle arrest and inhibiting tumor cell proliferation." (PMID 38711992, 2024). "Downregulation of lncRNA HOXA-AS3 blocked the tumor development via sponging miR-29c and upregulating CDK6 in pancreatic cancer." (PMID 39019995, 2024). "The study suggested that overexpression of miR-584 acts as a tumor suppressor, which can disrupt binding between hnRNP A1 and CDK6 mRNA, leading to apoptosis." (PMID 38632250, 2024). "Recent studies have identified novel CDK4/CDK6 inhibitors with improved efficacy in inhibiting MM cell proliferation and tumor growth." (PMID 39664374, 2024). "In this study, we used Crisper-Cas9 technology to generate Cdk4 and Cdk6 knockout cell lines to elucidate the role of CDK4 and CDK6 in anti-tumor immunity accurately." (PMID 37833461, 2023). "The p16 gene product plays a relevant role in tumor suppression by inhibiting the key cell cycle-related proteins CDK4/CDK6." (PMID 37132663, 2023). "Cyclin-dependent kinases CDK4 and CDK6 not only contribute to cell cycle progression but also participate in cell metabolism, immunogenicity and anti-tumor immune responses." (PMID 37686364, 2023). "We indeed show that in two CDK6-dependent tumor cell models, depletion of SENP3 or SENP5 downregulates CDK6 and affects cell proliferation." (PMID 38065954, 2023). "While targeting CDK6 can directly inhibit tumor cell proliferation, we put forward a pathway by which blocking CDK4 and CDK6 in cancer cells enhance anti-tumor immune responses by inducing DNA damage-mediated, STING-dependent type I IFN production." (PMID 37833461, 2023).
tumor (continued). "A subset of tumor cell lines depends on high CDK6 expression and targeting of CDK6 is an emerging anti-cancer strategy." (PMID 38065954, 2023). "In the current studies, we addressed the mechanisms responsible for the anti-tumor immunity of CDK4 and CDK6 blockage using Cdk4−/− and Cdk6−/− tumor cells." (PMID 37833461, 2023). "Overexpressed IGF2BP2 in LSCC serves as an oncogenic factor, promoting LSCC cell proliferation and invasion in vitro and tumor growth in a xenograft tumor model in vivo through facilitating CDK6 mRNA stabilization." (PMID 37816718, 2023). "We next sought to determine which pathway was more important in Cdk6−/− mediated anti-tumor responses." (PMID 37833461, 2023). "For instance, lncRNA LOC100129620 has been implicated in the promotion of OS progression through the modulation of cyclin dependent kinase 6 (CDK6) expression, tumor angiogenesis and macrophage polarization." (PMID 37858131, 2023). "Overall, our clinical and laboratorial studies identified the similar but distinct role of CDK4 and CDK6 in anti-tumor responses." (PMID 37833461, 2023). "A combination of SCR-6852 and CDK4/CDK6 inhibitors revealed synergistically anti-tumor activities both in vitro and in vivo." (PMID 37580832, 2023). "In conclusion, overexpressed IGF2BP2 in LSCC serves as an oncogenic factor, promoting LSCC cell proliferation and invasion in vitro and tumor growth in a xenograft tumor model in vivo through facilitating CDK6 mRNA stabilization." (PMID 37816718, 2023). "Based on previously reported studies, it has been documented that IL1B, CXCL1, CDK6, and IGFBP3 were closely associated with tumor radiosensitivity." (PMID 37468464, 2023). "The work suggests that DNA damage induced by either Cdk4 or Cdk6 knockout triggers anti-tumor immune responses through the STING-dependent type I interferon response." (PMID 37833461, 2023). "We aim to find the similarities and differences between CDK4 and CDK6 in regulating tumor immunogenicity." (PMID 37833461, 2023). "We focus on CDK6 because previous work in cancer has highlighted its specific contribution to tumor angiogenesis." (PMID 37745444, 2023). "Noteworthy, along with Sp1, the reactivation of the oncosuppressive miR-29b was accompanied by the down-regulation of other miR-29b canonical targets, i.e., MCL-1 and CDK6, suggesting a pleiotropic anti-tumor activity of this drug in MM cells." (PMID 37759449, 2023). "Mechanistically, our results showed that Cdk4 and Cdk6 deficiency induced DNA damage, which activated STING-dependent Type I IFN response and anti-tumor immunity." (PMID 37833461, 2023). "Prior to treatment with ribociclib, patients’ tumor analyzations monitored cyclin D1/D3 amplification, CDK4/CDK6 amplification, CDK4/CDK6 mutations, and p16 mutations." (PMID 35884441, 2022). "Significant inhibition in tumour size, microvessel density, and expressions of Bcl-2 and CDK6 was observed in mice bearing tumours." (PMID 35457210, 2022). "Dual CDK4 and CDK6 inhibitors have been shown to be active in multiple preclinical models, including xenografts, genetically engineered mouse models and primary human tumor explants." (PMID 35053461, 2022). "MiR-124 acts as a tumor suppressor by inhibiting the translation of the cell cycle regulator cyclin dependent kinase 6 (CDK6) and by reducing the phosphorylation of the retinoblastoma protein (Rb)." (PMID 35326471, 2022). "Studies have shown that EZH2 (which contributes to tumor proliferation), and CDK6, a critical regulator of cell cycle transition in G1/S, are both upregulated in GBM and are direct target genes of miRNA-13834." (PMID 35835978, 2022). "Cell cycle progression is promoted by CDK6 through interaction with D-type cyclins to phosphorylate the retinoblastoma tumor suppressor and displays oncogenic potency by kinase activity in several types of malignant tumors." (PMID 35463324, 2022).